ALK (ALK receptor tyrosine kinase)
Diseases named in the same sentence as ALK in open-access papers (continued):
Sharing a sentence is not in itself a finding about the gene and the disease.
tumor (continued). "However, novel compounds targeting tumor‐specific molecular changes, such as EGFR and BRAF mutations, and ALK fusions, or immunomodulatory agents activating anti‐tumor immune responses, are challenging this paradigm, and some of these drugs show intracerebral efficacy." (PMID 32858763, 2020). "Therefore, we proposed research hypothesis for serum tumor markers, which is economical and convenient for every patient in the prediction of ALK mutations." (PMID 31489711, 2020). "In addition, advanced NSCLC patients could receive molecular targeted therapies (e.g., EGFRi, ALK inhibitors) according to tumour mutational status." (PMID 31540260, 2019). "For instance, in NSCLC patients with acquired resistance to anti-PD-1/PD-L1 immunotherapies and EGFR or ALK mutations, particularly for patients with high tumor burden or rapid disease progression, a combination of anti-PD-1/PD-L1 therapy and targeted therapy may be an option." (PMID 30159341, 2018). "Tumor mutation testing allows us to divide patients into three groups: patients with EGFR-positive tumor mutations (10–30%); patients with ALK rearrangements (4–7%); and patients with tumors who either do not have EGFR or ALK mutations, or their mutation status is unknown." (PMID 28373963, 2017). "In this context LB allows regular monitoring of patients treated with ALK inhibitors and therefore detection of mutations in blood at a very early stage with subsequent consequential modification of the therapeutic approach in the case of progression or relapse of the tumor." (PMID 29125548, 2017). "However, drug selective pressure and stochastic generating mutations may resensitise tumours to previously employed ALK TKI." (PMID 27433281, 2016). "Causes of resistance include tumor acquisition of a secondary mutation within the ALK tyrosine kinase domain, amplification of the ALK fusion gene (which may occur alone or in combination with a secondary resistance mutation), or development of alternative or bypass signaling pathways." (PMID 29282427, 2016). "However, a proportion of cases are genuine neoplasms with the involvement of ALK fusion mutations." (PMID 27846861, 2016). "To determine whether the silencing of ALK, independently of its mutational status, could improve the anti-tumor efficacy of the ALK-inhibitor X-396, we decided to introduce our well established NB-targeted nanoparticles entrapping siRNA for specific ALK-knockdown in the treatment schedule." (PMID 26299615, 2015). "Indeed, more recent large-scale sequencing studies have revealed that NB tumours have an average of only 12 amino-acid-changing mutations per tumour, with the highest recurring mutated gene, ALK, being mutated in only 6-10% of tumours, suggesting that the genome of NB is largely intact." (PMID 25786414, 2015). "Although NGS might not be the most cost-effective method for identification of only two mutations in an uncommon tumor, it becomes a more viable alternative to conventional Sanger sequencing if the region of interest covers most, or all, of the entire ALK gene." (PMID 25188507, 2014). "Moreover, non-direct inhibition of the PTN signaling pathway by ribozymes targeted at ALK gene mRNA (which encodes a tyrosine kinase receptor for PTN ) caused a 50-95% retardation of tumor growth and a two-fold increase in the mean survival time for mice with grafted glioblastoma." (PMID 22649602, 2009). "In addition, the type of ALK fusion may be associated with the primary site of the tumor." (PMID 41200062, 2026).
tumor (continued). "Advances in tumor molecular profiling have led to the identification of actionable oncogenic alterations, including rearrangements involving the anaplastic lymphoma kinase (ALK) gene, which occur in a distinct subset of NSCLC patients." (PMID 41797880, 2026). "Dysregulated kinase signaling particularly involving EGFR, PI3K/AKT/mTOR, MAPK, and ALK pathways drives tumor growth, survival, and metastasis." (PMID 41821616, 2026). "Of note, the two models in which the primary tumor clustered closest to allografts (ALK- and FGFR1-driven) had been cultured for eight and nine passages, respectively, whereas NTRK-driven tumor cells were only in culture for six passages." (PMID 41381884, 2026). "This ALK-fused tumor exhibited aggressive behavior, recurring after an initial wide local excision and progressing despite neoadjuvant immunotherapy with a PD-1 inhibitor." (PMID 41949015, 2026). "The patient was subsequently treated with lorlatinib, a third-generation ALK inhibitor, which induced rapid and near-complete tumour regression." (PMID 41869672, 2026). "To address this gap, we report an ALK-driven IFS-like neoplasm of the hand, which was managed using a multimodal approach with oral lorlatinib, a tyrosine kinase inhibitor that targets ALK, and conservative surgical resection." (PMID 41439260, 2026). "Multivariate analyses have identified tumour location, local invasiveness, multi-focal growth, positive surgical margins, ALK expression status and specific gene fusions as independent risk factors." (PMID 40980125, 2025). "Collectively, we demonstrated that PTPN2 was upregulated and played a critical role in promoting tumor growth and survival specifically in ALK+ ALCL." (PMID 40734623, 2025). "At the molecular level, increased EGFR autophosphorylation and upregulation of EGFR ligands reactivate downstream cascades such as the phosphatidylinositol 3-kinase (PI3K)/AKT and MAPK/ERK pathways, enabling tumor cells to reduce dependence on ALK signaling." (PMID 40873540, 2025). "Liquid biopsy-based monitoring of circulating tumor DNA (ctDNA) allows serial detection of emergent resistance alterations, such as secondary EGFR or ALK mutations and MET amplification, often before radiographic progression." (PMID 41472727, 2025). "Clinical variables assessed included demographic data, comorbidities, Eastern Cooperative Oncology Group (ECOG) performance status, tumor characteristics, genetic mutations (EGFR, ALK, ROS1), treatment responses, toxicity profiles, and survival outcomes." (PMID 40805843, 2025). "Tumor cells circumvent ALK dependency by initiating or upregulating alternative receptor tyrosine kinases (RTKs) and their downstream signaling cascades, thereby sustaining cellular proliferation and survival." (PMID 41614760, 2025). "The largest compilation of primary CNS ALCL identified 39 cases, with 28 ALK-positive and 11 ALK-negative tumours; the median age was 17.5 years for ALK-positive tumours and 63 years for ALK-negative tumors, and the overall median age was 21 years." (PMID 41523563, 2025). "Exosomes polarizing fibroblast from bone marrow to cancer-associated fibroblast (CAF) in ALK+ ALCL have been described, altering the cytokine profile of the microenvironment, contributing to tumor aggressiveness and resistance to treatment." (PMID 40565334, 2025). "Specifically, both Erastin and RSL3 were able to resensitize CAF-CM-treated tumor spheroids to ALK inhibition." (PMID 40524253, 2025).
tumor (continued). "We have demonstrated that PTPN2 promotes mitochondrial renewal through PINK1‐PRKN‐dependent mitophagy by suppressing TFRC expression, thereby exerting tumor‐promoting effects in ALK+ ALCL." (PMID 40734623, 2025). "When DCTN1 undergoes a gene fusion with ALK, DCTN1 is suspected to promote the dimerization of ALK and lead to the abnormal activation of the ALK kinase by transphosphorylation, thereby promoting the proliferation and survival of tumor cells." (PMID 41246301, 2025). "The open-label, randomized, single-center translational study (NCT06893354) aims to investigate the tumor microenvironment remodeling following lorlatinib induction therapy in surgically resectable ALK-positive NSCLC." (PMID 40563563, 2025). "Additionally, this ADC utilized a chimeric ALK-directed antibody, which carries an immunogenicity risk compared to humanized antibodies due to the formation of human anti-mouse antibodies that leads to rapid clearance, poor tumor penetration, and hypersensitivity reactions." (PMID 40813394, 2025). "This successful personalized anti-tumor strategy highlights the clinical utility of comprehensive genomic profiling and liquid biopsy in detecting and monitoring actionable ALK fusions in solid tumors." (PMID 41246301, 2025). "In this study, we propose to use the functional assay DBP to complement FISH or IHC techniques by directly evaluating the cytotoxicity of ALK inhibitors on living tumor cells." (PMID 40113795, 2025). "In vivo, CDX-0125-TEI significantly reduced tumor growth in NB mouse models, effectively targeting both wild-type (WT) and mutant ALK in patient-derived xenografts while sparing healthy cells due to its specificity." (PMID 40129921, 2025). "It reminded that pathologists should be aware of the possibility of other ALK-positive neoplasms, including metastatic lesions, in the diagnosis-making process." (PMID 40224190, 2025). "Tumor growth suppression and survival were substantially improved in both RDAA-positive NSCLC cell line-derived and patient-derived xenograft tumor models treated with ALK inhibitors." (PMID 40246819, 2025). "Anaplastic lymphoma kinase (ALK) fusions are critical oncogenic drivers of tumor growth and proliferation across a broad number of solid tumors but are considered to be rare." (PMID 40338218, 2025). "Epithelioid fibrous histiocytoma (EFH) is a benign fibrohistiocytic neoplasm characterized by morphologic heterogeneity and recurrent anaplastic lymphoma kinase (ALK) gene rearrangements." (PMID 40688914, 2025). "In contrast, more survival tumor cells were observed in control and LA tumors, indicating that tumors with LA fusion were resistant to ALK‐TKI." (PMID 40151836, 2025). "Pretreatment and post‐treatment resistant tumor samples from EGFR‐mutant or ALK‐positive patients demonstrate that SCLC transformation is one of the resistance mechanisms leading to tumor histological changes and independence from the original signaling axis." (PMID 41415713, 2025). "In ALK-TKI resistance, PI3K/AKT activation often occurs independently of ALK signaling, supporting tumor growth by suppressing pro-apoptotic proteins and amplifying anti-apoptotic signals." (PMID 40873540, 2025). "The biomarkers investigated included Programmed death-ligand 1 (PD-L1), Epidermal growth factor receptor (EGFR), Anaplastic lymphoma kinase (ALK), Kirsten rat sarcoma (KRAS), and others associated with tumor proliferation and therapeutic response." (PMID 40078179, 2025). "Immunohistochemically, the tumor cells were diffusely ALK-positive, focally positive for α-smooth muscle actin and desmin (inset), and negative for ROS1, SOX10, and CD10." (PMID 40557015, 2025). "SHP2 inhibitors have shown promise in preclinical studies of EGFR-mutant and ALK fusion-positive tumours with activation of MAPK pathway." (PMID 40849356, 2025).
tumor (continued). "To investigate the clinical association of PTGDS in PTCL patients, we performed further analysis and found that the high expression of PTGDS in tumor tissue was statistically correlated with ALK+ ALCL (p = 0.008) and elevated ESR (p = 0.004) in PTCL patients." (PMID 39706989, 2025). "The antibody clone 5A4 has shown excellent sensitivity (100%) and modest specificity (75%) in detecting the ALK gene rearrangement in PTCs, seen as diffuse expression in the cytoplasm of tumor cells." (PMID 40111709, 2025). "Using the pan-HDACi Vorinostat and the class I-specific inhibitor Entinostat, we previously showed high sensitivity of murine ALK+ tumor cell lines, resulting in DNA damage and apoptosis following 48 h of treatment." (PMID 40175628, 2025). "ALK+ ALCL had a higher expression of PD-L1 in the tumor cells, in contrast to ALK- ALCL, which expressed high PD-L1 in TAMs." (PMID 40565334, 2025). "ALK rearrangement was higher in patients with low expression, and PD-L1-positive patients had a larger tumor diameter than those with PD-L1-negative tumors." (PMID 40624192, 2025). "Our preclinical studies using cell line-derived xenografts and several PDX models provide compelling data on the ant-tumor activity of ESK440 in ALK-driven NB models." (PMID 39900433, 2025). "Although RTK genetic alterations in NB are limited to 7–10% tumours with ALK mutations, the NB origin from NCC gives NB tumours a wide repertoire of targetable RTKs." (PMID 41511287, 2025). "Jude’s Human Tumor Atlas Project supported higher expression of ALK in ADRN and sympathoblast clusters and similar expression of SLC6A2 across ADRN/MES subtypes." (PMID 39825754, 2025). "ALK alterations are associated with poor prognosis and suppressing the expression or inhibiting the activity of ALK in cells with a mutant form or overexpression of ALK have been shown to reduce the cell and tumour growth rate." (PMID 41511287, 2025). "This case underscores the potential of Iruplinalkib, which is currently not available outside of China, to induce rapid and profound tumor regression in ALK-positive NSCLC, particularly in adolescent patients with aggressive clinical presentations." (PMID 40786512, 2025). "•Transurethral resection of tumor is said to be choice of management but partial cystectomy is also alternative.Crizotinib, an anaplastic lymphoma kinase (ALK) inhibitor can be considered for selected patients." (PMID 39921988, 2025). "Fusion of the ALK gene leads to the continuous activation of the kinase, thus driving the growth and proliferation of tumor cells." (PMID 41472727, 2025). "Oral PTPN2 inhibitor ABBV‐CLS‐484 disrupts mitochondrial renewal and blocks TFRC‐mediated mitophagy to exert anti‐tumor activities, supporting clinical development for ALK+ ALCL." (PMID 40734623, 2025). "No statistical differences were found between IPI score, clinical stage, tumor location, and ALK expression with disease outcome." (PMID 40635103, 2025). "Following the success of ADAURA in EGFR-mutated tumours, the phase III ALINA trial evaluated 2 years of adjuvant alectinib versus standard PBC in patients with ALK-rearranged stage IB-IIIA (TNM7) resected NSCLC." (PMID 40628491, 2025). "The average ALK H-score for each tumor was used for analysis when duplicate or triplicate cores were provided for a single tumor." (PMID 40813394, 2025). "For unresectable or recurrent ALK/ROS1 fusion–positive tumours, targeted tyrosine kinase inhibitors, such as alectinib, can be beneficial." (PMID 41368177, 2025). "Tumor-secreted RNase1 also induces TAM polarization toward a tumor-promoting phenotype via the ALK signaling pathway, suppressing CD8+ T cell activity." (PMID 40764998, 2025). "Phenotypic transformation represents a critical mechanism underlying resistance to ALK inhibitors, primarily manifested through EMT and SCLC-like conversion, enabling tumor cells to escape ALK-dependent signaling." (PMID 41614760, 2025).
tumor (continued). "The perioperative setting has been only partially explored for patients with EGFR-mutant or ALK-rearranged tumours." (PMID 40628491, 2025). "Clinically, it has demonstrated a strong anti-tumor effect as a single drug and superior growth inhibition compared to crizotinib, a first-generation ALK inhibitor." (PMID 40968384, 2025). "Such dysregulation markedly promotes tumor cell proliferation and survival and plays a critical role in mediating resistance to ALK-targeted therapies." (PMID 41614760, 2025). "Anaplastic lymphoma kinase (ALK) plays important roles in tumorigenesis and is involved in tumor immunogenicity through various pathways." (PMID 41716637, 2025). "Upregulation of immune checkpoint molecules such as PD-L1 represents a key mechanism by which tumor cells evade immune surveillance following resistance to ALK-targeted therapy." (PMID 40873540, 2025). "Mutations in neurofibromatosis-related protein (NF1), NRAS, and HRAS genes were found in tumours that developed resistance to lorlatinib or ceritinib, and NF1 loss conferred resistance to ALK inhibitors in NB cells." (PMID 41511287, 2025). "In summary, alectinib for locally advanced ALK-rearranged NSCLC produced a profound tumor regression that enabled R0 salvage resection with a pCR." (PMID 41036487, 2025). "ALK rearrangement was higher in patients with low-expression, and PD-L1-positive patients had bigger tumor diameter." (PMID 40624192, 2025). "EMT-associated resistance has been partially reversed in both in vitro and in vivo models through targeting TGF-β, Wnt/β-catenin pathways, and epigenetic modulators, thereby restoring tumor sensitivity to ALK inhibitors." (PMID 41614760, 2025). "The most common method for detecting these rearrangements is fluorescence in situ hybridization (FISH), with ALK positivity identified by the presence of ALK immunopositivity or FISH-detected ALK rearrangement in at least 15% of tumor cells." (PMID 39980542, 2025). "ALCL is a common type of tumor that harbors ALK gene fusion; furthermore, about 10% of ALCLs present large round neoplastic cells admixed with a large number of reactive histiocytes, which is similar to the morphology of the present case." (PMID 40224190, 2025). "Although targeted therapies are effective in patients with ALK rearrangements, drug resistance and tumor recurrence inevitably occur." (PMID 40376302, 2025). "For example, in ALK intron 19, the boxplots of the target-level coverage distribution between tumor types are provided below (ALK intron 19 target-level coverage for clinical samples with QC status = Pass, clinical samples with QC status = Qualified." (PMID 40748987, 2025). "Our study revealed that after neoadjuvant therapy, ALK-positive NSCLC transitions from an immunologically “hot” tumor to a “cold” tumor with decreased infiltration of CD8+ cells and macrophages, as well as a lower M1/M2 macrophage ratio." (PMID 40071084, 2025). "Mutations in ALK, found in 12-14% of HRNB cases, activate downstream pathways PI3K/Akt and MAPK, promoting tumor cell survival and proliferation." (PMID 40104501, 2025). "Future research is required to evaluate this trend in a larger, more diverse cohort and investigate the roles of environmental factors and tumor microenvironments in influencing ALK alteration prevalence." (PMID 39807831, 2025). "The oncogenic signaling pathway mutations consisted of KRAS, EGFR, and ALK/ROS1/RET mutations, which play crucial roles in cell proliferation and are associated with tumor aggressiveness and a higher risk of recurrence." (PMID 40507370, 2025). "Fusion partners are diverse, including TPM3, TPM4, CLTC, and ATIC, and the resultant chimeric proteins mediate constitutive ALK activation, promoting aberrant cellular proliferation and remodeling of the inflammatory tumor microenvironment." (PMID 41614760, 2025).